EGFR (epidermal growth factor receptor)
Diseases named in the same sentence as EGFR in open-access papers (continued):
Sharing a sentence is not in itself a finding about the gene and the disease.
cancer (continued). "The blebbing was also observed with high concentrations of a physiologically relevant molecule EGF to stimulate EGFR in cancer cells." (PMID 29702613, 2018). "EGFR is overexpressed in a number of malignant tumors, like carcinomas of head and neck, breast, urinary bladder and lung." (PMID 29728916, 2018). "In this study we investigated a role for BAG3 in driving cancer cell proliferation in TNBC models by stabilising EGFR signalling nodes." (PMID 29644001, 2018). "Although EGFR-TKIs are effective as anti-cancer drugs, cancer cells sometimes gain tolerance to the drugs." (PMID 30075033, 2018). "A polymer CTC-chip microfluidic device was surface-functionalized with three different anti-EGFR antibodies and used to capture EGFR-expressing cancer cells." (PMID 30104638, 2018). "One of the best-known anti-angiogenic therapies for cancer treatment had adopted VEGF inhibition (bevacizumab) in combination with EGFR tyrosine kinase inhibitor (Erlotinib) for patients with recurrent non-small-cell lung cancer." (PMID 29342116, 2018). "Here, the authors show that genotoxic stress induces senescence in human stromal cells, which in turn secrete serine protease inhibitor Kazal type 1 (SPINK1) and promote acquired resistance of cancer cells via EGFR-mediated paracrine signaling." (PMID 30333494, 2018). "Activation of IGF1R is another mechanism conferring the acquired resistance against gefitinib to EGFR-amplified and EGFR-mutant cancer cell lines." (PMID 29455669, 2018). "We thoroughly characterize the properties of the nanocarriers and evaluate the anti-cancer therapeutic efficacy both in vitro and in vivo using high EGFR-expressing CT-26 murine colorectal cells." (PMID 29584656, 2018). "Inside the cell, EGFR is imported to the nucleus by Importin β1 and associates with activated STAT3, and potentially other transcription factors, to induce the expression of nuclear EGFR target genes, thereby promoting cancer cell proliferation." (PMID 29599917, 2018). "Previous studies reported that EGFR promotes DNA replication of cancer cell by Lyn phosphorylation, and Lyn kinase regulates phosphorylation of EGFR through PKCβII." (PMID 29892225, 2018). "Ras/Raf-MAPK, FGF, and EGFR signaling all have well-documented roles in cancer progression as well, as is the case in ASP development." (PMID 30018198, 2018). "Previous studies have shown that Sym004 is more efficient at inducing internalization and degradation of EGFR than individual components, which translates into superior cancer cell inhibition." (PMID 29564747, 2018). "The higher expression level of EGFR that cancer cells harbored, the greater inhibition efficiency that Lycorine displayed." (PMID 30016965, 2018). "Such balance between receptor signaling and degradation is prudently maintained in normal cells but frequently decoupled in cancer cells overexpressing EGFR." (PMID 29976202, 2018). "The epidermal growth factor receptor (EGFR) has evolved over the years into a main molecular target for the treatment of different cancer entities." (PMID 29777377, 2018). "We postulate that CXCL1 and 8 potentiate EGFR transactivation in TNBC cells to enhance the cancer aggressiveness and chemoresistance." (PMID 30034618, 2018). "Further studies with increasing number of patient cases are required to determine correlations between EGFR and three GGAs in cancer tissues." (PMID 29358589, 2018). "During cancer cell proliferation, the activation of epidermal growth factor receptor (EGFR) and its downstream target, extracellular signal regulated protein kinases ERK1/2, are also required." (PMID 30213130, 2018). "As a well-known oncogene that is critical to tumorigenesis, EGFR has been evaluated in clinical trials as the target of effective cancer therapies by mAbs (e.g., cetuximab and panitumumab) or TKIs (e.g., erlotinib, gefitinib, afatinib, and osimertinib)." (PMID 30449278, 2018).
cancer (continued). "It is well known that MDR1, EGFR, and STAT3 are in significant associations with the multidrug resistant of cancer cells." (PMID 29872398, 2018). "We showed that IRDye-800CW-nimotuzumab binds to a variety of EGFR positive human cancer cell lines in vitro and in vivo." (PMID 29464066, 2018). "In both these studies, the efficacy of MNT-delivered AEEs targeted at cancer cells with EGFR overexpression was compared with the efficacy of the same AEEs (125I and 67Ga) attached to EGF." (PMID 30210340, 2018). "It indicated that these blockades of EGFR and its downstream signal pathways further decreased the expression of PD‐L1 on cancer cell membranes by inhibiting the activity of mTOR signal pathway." (PMID 29533017, 2018). "This rise was due to alterations at a low percentage in genes with proven predictive value in the context of approved anti-cancer drugs (e.g., EGFR, BRAF, ERBB2, BRCA1, BRCA2, RET, ALK) in all cancer types." (PMID 29544535, 2018). "EGFR is an ideal candidate as target cancer epitope as it is often overexpressed in cancer cells and over-expression is associated with advanced disease, poor prognosis, and resistance to therapy." (PMID 30287819, 2018). "Crosstalk between Notch1 and EGFR signaling in cell proliferation and cancer expression has been observed in genomics and can be either synergistic or antagonistic depending on the different contexts." (PMID 29321718, 2018). "EGFR inhibitors represent a showcase for the therapeutic power of precision cancer medicine in genetically selected patients." (PMID 30405134, 2018). "The drugs targeting the EGFR-RAS-ERK pathway, such as the anti-EGFR antibody drugs including cetuximab and panitumumab, have been prescribed as therapeutic drugs for patients with cancers such as metastatic CRC." (PMID 30459318, 2018). "Upon inspection of the coding sequence, we noted that the 5′ bystander mutation is synonymous, whereas the 3′ bystander results in a premature stop codon (TAG), which is much less likely to be tolerated in this EGFR-dependent cancer cell line." (PMID 30593278, 2018). "EGFR is frequently overexpressed in most cancers of epithelial origin where it promotes enhanced proliferation and confers resistance to targeted therapies." (PMID 29682209, 2018). "Epidermal growth factor receptor (EGFR) is an important oncogene closely involved in many cancer types, and its gene product is a transmembrane glycoprotein belonging to the tyrosine kinase receptor family." (PMID 29666782, 2018). "To ask how ALDH7A1 levels correlate with EGFR activity in these cancers, we used reverse-phase protein array data on EGFR phosphorylation, which provides a measure of EGFR pathway activation in the tumors." (PMID 30486822, 2018). "It was assumed that virtually all types of epithelial malignancies are characterized by some involvement of EGFR activation, therefore EGFR-directed therapies were expected to be efficient in a wide spectrum of cancers." (PMID 30211169, 2018). "A correlation between the carcinogenicity of the asbestos fibers and the induction of phosphorylation of EGFR was observed in rat pleural mesothelial cells, suggesting its potential role in the pathogenesis of this cancer." (PMID 29666782, 2018). "In this regard, several pathways enriched in lSSc and/or dSSc (apoptosis, glycolysis, PDGF, Fas cell surface death receptor, FAS, angiogenesis, interleukin, Ras, Jak/Stat, and EGFR signaling pathways) are involved in cancer development." (PMID 29559981, 2018). "Other than simply correlating Axl expression to induction of resistance in cancer, several reports described the ability of Axl to dimerize with other receptors, such as EGFR, MET, and platelet-derived growth factor (PDGFR)." (PMID 30322068, 2018). "Since EGFR plays a central role in the progression of several types of cancer, significant effort has been put forth into developing therapies that target EGFR function." (PMID 30108171, 2018).
cancer (continued). "This study also used in vitro therapeutic screening for identifying the targeted agents against EGFR-positive CRCs and their derived cancer stem-like tumorspheres." (PMID 30068339, 2018). "Inappropriate N-, and O-glycosylation often results in malfunction of EGFR—a validated oncogenic target in cancers, such as lung and breast." (PMID 29541627, 2018). "EGFR is frequently reported to be overexpressed in HNSCC, and such overexpression correlates with poor prognosis: almost 80% of HNSCC studies demonstrate decreased OS and DFS for patients with cancers overexpressing EGFR." (PMID 30619735, 2018). "Down-regulation of EGFR or HER2 can enhance sensitivity to anti-cancer drugs, such as EGFR inhibitors." (PMID 30583572, 2018). "These GScores underline the biological relevance and clinical utility of both KRAS and EGFR genomic alterations in cancer." (PMID 29848362, 2018). "Several genes account for a large proportion of variant/drug interactions (e.g., EGFR, KIT, ERBB2, BRCA1, PDGFRA), reflecting interest in therapeutically exploiting a relatively limited number of cancer driver genes." (PMID 30053901, 2018). "Signaling pathways related to the epidermal growth factor receptor (EGFR) such as EGFR/PI3K/AKT-mTOR pathway command a unique position in cancer biology." (PMID 29713280, 2018). "Clearly, we need to improve the molecular characterization of tumors from CRC patients in order to identify the molecular alterations inside cancer cell genomes that drive cancer growth and determine the inefficacy of anti-EGFR/VEGF targeted therapies." (PMID 29665843, 2018). "EGFR promotes cell migration and invasion signaling in cancer cells through activation of cell adhesion, SRC, AKT, MAPK and endosomal signaling pathways." (PMID 29455656, 2018). "Cancer cells express high levels of Eps8 and EGFR among the cell lines that we have examined were treated with peptide 327 and TAT-327 (50 μM) for 12 h." (PMID 29515106, 2018). "Though magnesium is essential to organism, how hypomagnesemia relates to efficacy of these anti-EGFR MoAs and what effect magnesium levels have on cancer progression is an uncertain area of research with contradicting results." (PMID 29391418, 2018). "Capture efficacy depended on the type of antibody used, and cetuximab efficiently captured cancer cell lines that had a wide range of EGFR expression." (PMID 30104638, 2018). "Our data suggest a new therapeutic potential to block cancer metastasis by targeting AR, EGFR and MMP-9 pathways in subsets of PCa patients." (PMID 30134822, 2018). "The increased uncontrolled CME rate causes increased EGFR recycling and signaling through AKT, promoting cancer cell survival." (PMID 29124875, 2018). "EGFR is a cell surface receptor tyrosine kinase in ErbB family and has been an attractive therapeutic target for various human cancers including HNSCC." (PMID 31093356, 2018). "Epidermal growth factor receptor (EGFR) or HER1, which resides on the surface of the cancer cell, remained the most utilized target, accounting for 27 (15%) of the 178 trials in our review." (PMID 29765563, 2018). "As previously suspected, with amplification of EGFR and HER2 in hM1 cells, the pan-ErbB inhibitors, Afatinib, and Neratinib, were very effective against hM1 cancer cells." (PMID 29599906, 2018). "The EGFR is a validated target for cancer therapy; however, resistance to EGFR inhibitors eventually evolves." (PMID 29455655, 2018). "In this study, we aimed to provide useful preclinical data to further facilitate a phase I clinical trial for patients with advanced EGFR-positive cancers." (PMID 29415996, 2018). "With the introduction of the Epidermal Growth Factor Receptor/Tyrosine Kinase inhibitors (EGFR-TKIs), which target cancer cells harboring activating EGFR mutations, the detection of somatic mutations became relevant to treatment choices for lung ADC." (PMID 29368620, 2018).
cancer (continued). "To prove that cigarette smoke renders NSCLC cancer cells more resistant to EGFR TKI through induction of c‐MET signaling, we first confirmed the c‐MET activation in H292/B[α]P cells by western blot analysis." (PMID 29570930, 2018). "Following this, genetic testing as an effort to classify cancer patients between EGFR(+) and KRAS(+) before prescribing anti-EGFR mAbs have been emphasized worldwide." (PMID 30042874, 2018). "Cetuximab is a recombinant human-mouse chimeric mAb against EGFR and exhibits antitumor activity against various cancers." (PMID 30321186, 2018). "NKP also modulates the activity of various signaling molecules important for cancer pathogenesis such as epidermal growth factor receptor (EGFR), mitogen-activated protein kinase (MAPK) and the PI3K/Akt/mTOR pathway." (PMID 29590154, 2018). "One of these proteins is epidermal growth factor receptor (EGFR), which is upregulated in different types of cancer, and has been the target for a class of anticancer drugs known as EGFR inhibitors (EGFRIs)." (PMID 30289881, 2018). "Among the molecules contributing to tumorigenesis, epidermal growth factor receptor (EGFR) has been recognized to induce neoplastic transformation in the presence of ligands and its overexpression is characteristic of several cancer cell lines." (PMID 30587839, 2018). "The expression of EPH receptor A2 (EPHA2) is activated by EGFR and EGFRvIII in the human cancer cell lines." (PMID 29423044, 2018). "In turn, TGF-α secreted by these fibroblasts promoted metastasis via induction of EGFR signaling in cancer cells." (PMID 30103384, 2018). "We postulated the high expression of EGFR on the hypoxic TNBC cells can be exploited to achieve enhanced delivery of cancer therapeutics to the cells." (PMID 30347860, 2018). "Given the correlation between poor prognosis and EGFR overexpression in several types of cancers, anti-EGFR agents have become a major class of targeted therapy, albeit, with rarely complete responses and eventual drug resistance in most cases." (PMID 30127519, 2018). "Over the decades, many bacterial- or plant-based immunotoxins have been developed with the aim of targeting a variety of cancers reliant upon EGFR overexpression." (PMID 30596104, 2018). "Previous work, along with pre‐clinical and clinical data presented herein, supports the view that EGFR activation can in turn substitute for MET signaling in MET‐driven cancer cells." (PMID 30021798, 2018). "Passive diffusion is often assumed to be the main mechanism for erlotinib to enter cancer cells and reach the EGFR kinase domains." (PMID 30116910, 2018). "Since, the overexpression of EGFR stimulates tumorigenesis, angiogenesis, and metastasis, blocking of EGFR pathway is one of the major strategies for targeted cancer therapy." (PMID 30323297, 2018). "Epidermal growth factor receptor (EGFR) was evaluated as a target antigen for cancer cell capture by microfluidic methods based on antigen-antibody association." (PMID 30104638, 2018). "To achieve this, we developed a system to couple esiRNA to the cancer cell-specific anti-EGFR-antibody cetuximab which delivers esiRNA to the intended cancer cells, binds to the EGFR receptor and gets internalized in a receptor-dependent fashion." (PMID 30001368, 2018). "At the moment, most cancer treatments are combinations of chemotherapeutic agents and/or radiotherapy, and it is expected that new EGFR‐targeted agents will achieve their greatest efficacy in combination with traditional cytotoxic agents and/or radiotherapy." (PMID 29603584, 2018). "The effects on EGFR expression of both T4 and tetrac are highly consistent with their proposed roles as promoter and inhibitor of cancer metastasis, respectively." (PMID 30135398, 2018). "COX-2 inhibitors have found to be a treatment option in anti-EGFR resistant cancers of metastatic CRC." (PMID 30602942, 2018).
cancer (continued). "When comparing fusion events with the remainder of the cancer cohort, fusions involving oncogenes such as EGFR, ERBB2, and RET had increased expression." (PMID 29617662, 2018). "Two studies reported that some NSCLC patients were sensitive to EGFR inhibitors, and when the TKIs were interrupted that would lead cancer progression to accelerated." (PMID 30337598, 2018). "Unfortunately, although the great benefit obtained with the EGFR-TKIs, cancer cells inevitably develop resistance, commonly within a median time on treatment of 10–12 months, leading to treatment discontinuation as consequence of disease progression." (PMID 30190486, 2018). "Epidermal growth factor receptor (EGFR) has been shown to have abnormal expression in many human cancers and is considered as a marker of poor prognosis." (PMID 29879970, 2018). "In contrast to the bivalent α-EGFR-EGFR TM, the monovalent α-EGFR TM is less efficient and mediates solely a significant eradication of cancer cells with high EGFR density." (PMID 29876011, 2018). "TKIs and mAbs are currently the main approaches for targeting EGFR in manifold human cancer therapies." (PMID 30404198, 2018). "(B) Heatmap of the correlation between ALDH7A1 mRNA expression and EGFR RNA and EGFR phosphorylation in all cancer types." (PMID 30486822, 2018). "EGFR plays a significant role in cancer progression, not only by transducing growth signals into cancer cells, but also by triggering invasion and metastasis." (PMID 29535630, 2018). "Loss of a tumor suppressor gene, such as PTEN, and amplification of a proto-oncogene, such as EGFR, both lead to cancer progression." (PMID 29342193, 2018). "Expression and activation of EGFR, therefore, plays a key role in anoikis resistance of cancer cells." (PMID 30237423, 2018). "Up to now, cancers have been treated with surgery, chemotherapy, radiotherapy, and targeted molecular therapy including EGFR-TKI (epidermal growth factor receptor-tyrosine kinase inhibitor)." (PMID 29971244, 2018). "Various studies found that ER expression is inversely correlated with EGFR or cancer stem cell phenotype and that is well supported by the data that indicate higher expression of EGFR and presence of stem cell population in TNBCs which lack ER expression." (PMID 29455658, 2018). "Patients undergoing both KRAS and EGFR testing lived an average of 66 miles away from an NCI cancer center compared to 85 miles for those undergoing EGFR testing." (PMID 29554880, 2018). "In our present study, actein suppressed the expression of phosphorylation of EGFR in human triple negative MDA-MB-231 cancer cells." (PMID 30618758, 2018). "A number of cancer drugs inhibit proteins that have been shown to localize to cilia, such as EGFR and PDGFR." (PMID 29874589, 2018). "PGRMC1 appears to interconvert between the apo-monomer and the heme-stacked dimer in response to an increase in heme levels in cells, and stimulates cancer proliferation and chemoresistance by binding to EGFR or cytochrome P450." (PMID 30087538, 2018). "Next, we considered high mEGFR and nEGFR expression together as total EGFR (tEGFR) expression, defined as either high mEGFR or nEGFR expression, to investigate the treatment response in patients receiving different anti-cancer therapies." (PMID 29950164, 2018). "This mutation enhances ATP affinity and reduces the ability of ATP-competitive reversible EGFR-TKI binding to EGFR tyrosine kinase domain, which results in cancer cells resistant to gefitinib and erlotinib." (PMID 29713646, 2018). "Recently, a drug-tolerant cancer cell subpopulation commonly affected by all EGFR-TKIs was recognized as a critical target." (PMID 30291293, 2018). "Nevertheless, our results show that HPV16-positive cancers display lower EGFR levels but higher pEGFR/EGFR ratios than HPV-negative cancers." (PMID 30619735, 2018).